MBD2 (methyl-CpG binding domain protein 2)
Diseases named in the same sentence as MBD2 in open-access papers (continued):
Sharing a sentence is not in itself a finding about the gene and the disease.
breast cancer (continued). "However, the exact role of Mbd2 in various stages of breast cancer growth and progression in vivo has not been determined." (PMID 38556549, 2024). "Although the mechanisms are not elucidated, menopausal effects on the role of MBD2 in breast cancer development may be related to changes in sex hormone levels." (PMID 16168120, 2005). "Moreover, Mbd2 protein expression was markedly increased in mammary fat pads (mfp) and primary tumors obtained from transgenic PyMT mice compared to the fat pads of WT C57BL/6 mice, indicating that Mbd2 upregulation mediated by the PyMT gene precedes the appearance of measurable mammary tumors." (PMID 38556549, 2024). "Although these assays were not quantitative enough to monitor potential changes in MBD2 deposition by ChIPseq, ChIP assays indicated that CAF-CMs can reduce MBD2 deposition at several upregulated genes, in SKBR3 and AU565 breast cancer cell lines." (PMID 29058695, 2017).
pulmonary fibrosis (15 papers, 2021 to 2025). Chronic progressive interstitial lung disorder characterized by the replacement of the lung tissue by connective tissue, leading to progressive dyspnea, respiratory failure, or right heart failure. "Less is known about MBD2 and ZBT14 in macrophages, although MBD2 has been linked to intestinal inflammation in mice and with an M2 macrophage programme in pulmonary fibrosis." (PMID 37073532, 2023). "Deletion of MBD2 in fibroblasts or myofibroblasts can protect against lung fibrosis in BLM-treated mice by inhibiting fibroblast differentiation into myofibroblasts." (PMID 40533455, 2025). "MBD2 is notably expressed at elevated levels in lung macrophages derived from individuals with IPF as well as in mice with bleomycin-induced pulmonary fibrosis." (PMID 38915445, 2024). "MBD2 was significantly upregulated in both SSc-ILD and IPF, while MBD2 depletion attenuated BLM-induced lung fibrosis in mice and suppressed TGF-β production and M2 macrophage accumulation." (PMID 37234611, 2023). "As a result, MBD2 has been well recognized to be involved in the pathogenesis of various diseases, including pulmonary fibrosis, obesity, ischemic injury, and autoimmunity." (PMID 36090987, 2022). "A more recent study reported that MBD2 promoted the differentiation of resting M0 macrophages to polarized M2 macrophages and then induced bleomycin-induced pulmonary fibrosis." (PMID 35136032, 2022). "Recent studies reported that Methyl-CpG–binding domain protein 2 (MBD2) promoted M2 macrophages accumulation to increase bleomycin-induced pulmonary fibrosis." (PMID 35136032, 2022). "On the one hand, MBD2 depletion protected against bleomycin-induced pulmonary fibrosis by a significant attenuation of TGF-β1 production, as well as a significant reduction in the accumulation of CD206+CD68+F4/80+ macrophage, but not of M1, in the lung." (PMID 34944564, 2021). "Notably, prior research has shown that MBD2 modulates the PI3K signaling pathway in macrophages through SHIP repression in lung fibrosis." (PMID 40467564, 2025). "Notably, depletion of MDB2 in mice attenuates bleomycin-induced pulmonary fibrosis by reducing TGF-β1 levels, and administering liposomal forms of MBD2 siRNA protects mice from bleomycin-induced pulmonary fibrosis." (PMID 35401519, 2022). "The methyl-CpG-binding domain 2 (MBD2) facilitates pulmonary fibrosis by orchestrating fibroblast-to-myofibroblast differentiation, and strategies aimed at silencing MBD2 can be potential therapeutic approaches for the prevention and treatment of pulmonary fibrosis." (PMID 36386240, 2022). "It was noted that Mbd2 may facilitate M2 phenotype polarization of macrophages during the process of pulmonary fibrosis." (PMID 36090987, 2022). "In this study, we illustrated that loss of Mbd2 in macrophages significantly diminished the M2-biased macrophage phenotype, implying that Mbd2 could also regulate macrophage M2 program in the setting of asthma, which was consistent with our previous data in pulmonary fibrosis." (PMID 36090987, 2022). "Multiple studies by Congyi Wang have shown that MBD2 levels are elevated in both IPF patients and bleomycin-induced pulmonary fibrosis model mice, particularly in the myofibroblasts within fibrotic lungs." (PMID 40533455, 2025). "CpG-binding domain 2 (MBD2) and matrix metalloproteinase 28 (MMP28) are two proteins that promote M2 polarization in pulmonary fibrosis." (PMID 37234611, 2023). "Similarly, the depletion of the gen Mbd2 attenuates the TGF‐β1 production and reduces M2 macrophage accumulation in lung fibrosis." (PMID 39031504, 2024).
asthma (14 papers, 2017 to 2025). "We did not see significant changes in Th2 cells differentiation during MBD2-OE, and silencing though silencing was associated with slightly higher Th2 cells than severe asthma." (PMID 36062195, 2022). "Estrogen (E2) increased the Th17 cells differentiation in severe asthma+E2 group, and OE and silencing of MBD2 were associated with increased and decreased level of Th17 cells, respectively." (PMID 36062195, 2022). "In conclusion, the data from this study demonstrated that MBD2-mediated Th17 cell differentiation is associated with reduced MINK1 expression in Th17-dominant asthma." (PMID 36303542, 2022). "The severe asthma+E2 group was associated with higher MBD2 expression, while the severe asthma+ DHT group greatly reduced the MBD2." (PMID 36062195, 2022). "Meanwhile, MBD2 KO mice were associated with comparatively less asthma symptoms, and interestingly, MBD2 was completely abolished in MBD2 KO mice." (PMID 36062195, 2022). "We confirmed that MBD2 expression was increased in patients with Th17 severe asthma and was associated with reduced lung function, suggesting that serum MBD2 contributes to the inflammatory process in patients with Th17 severe asthma." (PMID 34692717, 2021). "Transforming growth factor-β1(TGF β1) modulates allergic airway inflammation and remodeling in asthma, correlated with asthma severity, and is probably associated with MBD2 level." (PMID 35096261, 2021). "Similarly, in the BECs severe asthma model of our study, the correlative association between Th17 cells and MBD2 expression was also explored." (PMID 36062195, 2022). "In our recent review, we evaluated the correlative association of sex hormones fluctuation status, MBD2 expression, and Th17 cells, and postulated androgenic therapeutic potential in Th17 cells predominant neutrophilic severe asthma via regulating MBD2, and here performed this study." (PMID 36062195, 2022). "Severe asthma was associated with increased MBD2 expression and confirmed by its silencing and OE." (PMID 36062195, 2022). "In addition, MBD2 was found to be associated with poor lung function in patients with severe asthma." (PMID 34692717, 2021). "This also reveals the positive significance of MBD2 in linking both sex hormones and the nervous system in severe neutropenic asthma." (PMID 39800672, 2025). "In severe asthma, Th17 cells were abnormally elevated, with overexpression or silencing of the MBD2 gene leading to corresponding changes in Th17 cell numbers." (PMID 40533455, 2025). "Further analysis highlighted MBD2′s potential role in asthma pathogenesis and allergic reactions by influencing CD4+ T cell differentiation." (PMID 41008562, 2025). "Histological analyses revealed a marked decrease in MINK1 staining and increased methyl-CpG-binding domain protein 2 (MBD2) staining in the lungs of the mice in the Th17-asthma group." (PMID 39727954, 2024). "Consistently, the mRNA levels of MBD2 were elevated, while the levels of MINK1 mRNA were lowered, which suggests the involvement of MINK1 and MBD2 in the development of asthma phenotype and severity." (PMID 39727954, 2024). "We found that miR-146a-3p suppressed Th17 differentiation by targeting MBD2 in BECs of the severe asthma model." (PMID 36961677, 2023). "We performed immunohistochemistry (IHC) on mouse lung cells and found increased MBD2 immunopositivity in severe asthma compared to control group, but this was dramatically decreased in the miR-146a-3p agomir group." (PMID 36961677, 2023). "Here, we aimed to explore how miR-146a-3p interacts with MBD2 and affects the differentiation of Th17 cells in severe asthma." (PMID 36961677, 2023). "What is more, we measured the expression of MBD2 in peripheral blood serum by ELISA; the results showed that the expression of MBD2 was clearly increased in severe asthma patients compared to healthy controls (p < 0.01)." (PMID 36961677, 2023).
asthma (continued). "Taken together, these data indicated that miR-146a-3p mediates Th17 differentiation by targeting the MBD2 in Th17 predominant neutrophilic severe asthma." (PMID 36961677, 2023). "By targeting MBD2 to suppress Th17 cells differentiation, miR-146a-3p provides a potential novel therapeutic for Th17 predominant neutrophilic severe asthma." (PMID 36961677, 2023). "miR-146a-3p suppressed Th17 differentiation by targeting MBD2 to provide a potential novel therapeutic for Th17 predominant neutrophilic severe asthma." (PMID 36961677, 2023). "In this study, we first demonstrated that miR-146a-3p decreased in PBMCs and MBD2 increased in the serum of subjects with severe asthma patients." (PMID 36961677, 2023). "Taking all together, we come to the conclusion that miR-146a-3p suppressed Th17 differentiation in severe asthma by targeting MBD2." (PMID 36961677, 2023). "Meanwhile, the relative protein level of MBD2 in mouse lungs increased in the severe asthma group compared to the control group and was decreased in the miR-146a-3p agomir group." (PMID 36961677, 2023). "We noted comparatively higher MBD2 detection and expression in the severe asthma+ E2 group during its silencing than the silencing in severe asthma+ DHT and severe asthma+ DHT/E2 group." (PMID 36062195, 2022). "Lung histological analysis from the severe asthma group showed noticeably enhanced cells stained with MBD2 compared with the asthma group." (PMID 36062195, 2022). "The addition of the E2 in severe asthma+E2 group extensively increased the MBD2 stained cells, while the severe asthma+ DHT group markedly reduced MBD2." (PMID 36062195, 2022). "Th17-dominant asthma is mainly mediated by Th17 cells, and both MBD2 and MINK1 genes can affect the differentiation of Th17 cells." (PMID 36303542, 2022). "Studies were conducted in asthmatic patients and macrophage-specific Mbd2 knockout mice to dissect the role of MBD2 in asthma pathogenesis." (PMID 36090987, 2022). "This study is the first to evaluate the androgen therapeutic potential in severe asthma Th17 cells regulation via MBD2." (PMID 36062195, 2022). "A previous study showed that MBD2 was significantly increased in patients with Th17 severe asthma compared to healthy controls and patients with asthma." (PMID 36303542, 2022). "Previous studies have shown that MBD2 is involved in neutrophil-dominant asthma and positively regulates Th17 cell differentiation." (PMID 36303542, 2022). "In this study, MBD2 was significantly increased in lung tissues and BECs in the Th17-dominant asthma groups compared to that in T2 asthma groups." (PMID 36303542, 2022). "WB detected MBD2 protein expression in the animal model, and significantly higher MBD2 expression was observed in severe asthma." (PMID 36062195, 2022). "In the present study, we found that DHT attenuated BECs regulated Th17 cells (IL-17) differentiation and expression via regulating MBD2 in Th17 cells predominant neutrophilic severe asthma." (PMID 36062195, 2022). "Severe asthma + DHT group showed lower MBD2 detection and expression during OE as compared with OE in the severe asthma+ E2 and severe asthma+ DHT/E2 group." (PMID 36062195, 2022). "To further assess the role of MBD2 in macrophages during the development of asthma, we first generated a macrophage-specific Mbd2 knockout mouse model." (PMID 36090987, 2022). "Severe asthma was mediated by Th17 cells and MBD2-OE increased Th17 cells differentiation, while silencing showed the opposite results." (PMID 36062195, 2022). "DHT reduced the Th17 cells, while as usual MBD2-OE in severe asthma+ DHT group increased Th17 cells, and silencing was associated with decreased cells." (PMID 36062195, 2022). "Does sex hormone down-regulate MBD2 expression or directly affects the differentiation and the expression of the Th17 cells in severe asthma as a therapeutic potential?" (PMID 36062195, 2022).
asthma (continued). "DHT decreased all the markers of severe asthma (MBD2, Th17cells (IL-17), and RORγt) showing therapeutic potential, while E2 increased all the markers as it aggravated severe asthma." (PMID 36062195, 2022). "Methyl-CpG-binding domain protein 2 (MBD2) regulates the differentiation of the Th17 cells, showing the possibility of a therapeutic target in severe asthma." (PMID 36062195, 2022). "Our recent study also showed that MBD2 increases significantly in severe asthma and is a potential biomarker for identifying severe asthma various endotypes." (PMID 36062195, 2022). "MBD2 is involved in the differentiation of the Th17 cells in the pathogenesis of severe asthma where its overexpression increases the Th17 cells (IL17 protein) and silencing results in decreased expression as shown from our previous studies." (PMID 36062195, 2022). "We detected higher expression of MBD2 in severe asthma, and study has shown its involvement in severe asthma pathogenesis." (PMID 36062195, 2022). "The aim of this study was to evaluate how sex hormone interacts with MBD2 and affects the differentiation and expression of Th17 cells in severe asthma." (PMID 36062195, 2022). "The aim of this study was to investigate how MBD2 interacts with MINK1 to regulate Th17 cell differentiation in Th17-dominant asthma." (PMID 36303542, 2022). "These experiments demonstrate that MBD2 is involved in severe asthma via influencing Th17 cell development and IL-17 release." (PMID 36062195, 2022). "We conducted WB analysis to detect MBD2 under its silencing and overexpression in a cellular severe asthma model and under the influence of DHT, E2, and DHT/E2." (PMID 36062195, 2022). "Increased MBD2 expression and Th17 cells differentiation were noted in the animal and the BECs severe asthma models." (PMID 36062195, 2022). "In the present study, the results showed that compared to the asthma group, the histological analyses of lungs in the Th17-dominant asthma group showed significantly increased MBD2 staining and significantly decreased MINK1 staining." (PMID 36303542, 2022). "It has been reported that MBD2 is significantly increased in neutrophil-dominant asthma and positively regulates Th17 differentiation, while MINK1 negatively regulates Th17 cell differentiation, which has not been reported in Th17 dominant asthma." (PMID 36303542, 2022). "Increased detection and expression of MBD2, Th17 cells (IL-17), and RORγt were noted in severe asthma, and DHT decreased the detection and expression of all." (PMID 36062195, 2022). "The expression of MBD2 in lung tissues and BECs from the Th17-dominant asthma group was significantly increased, while the corresponding expression of MINK1 was significantly impaired." (PMID 36303542, 2022). "Secondly, the main purpose of this study was the role of MBD2 in asthma development and the potential feasibility of Mbd2 siRNA-loaded liposomes for therapeutic application." (PMID 36090987, 2022). "Collectively, these data support that macrophages derived from patients and mice with asthma are characterized by the induction of MBD2 overexpression." (PMID 36090987, 2022). "MBD2 detection in the severe asthma+ DHT group was lower than severe asthma, severe asthma +E2, and severe asthma+ DHT/E2." (PMID 36062195, 2022). "We induced Th17-dominant asthma mouse and BECs models and found that MBD2 was significantly increased in vivo and in vitro, while MINK1 was decreased, and there was a reverse expression between MBD2 and MINK1." (PMID 36303542, 2022). "At the same time, IL-17 protein expression increased significantly with OE of MBD2 and decreased with silencing showing the involvement of MBD2 in severe asthma by affecting Th17 cells differentiation and IL-17 secretion." (PMID 36062195, 2022).